IGF1 (insulin like growth factor 1)
Diseases named in the same sentence as IGF1 in open-access papers (continued):
Sharing a sentence is not in itself a finding about the gene and the disease.
neurodevelopmental disorder (24 papers, 2012 to 2026). A behavioral and cognitive disorder with onset during the developmental period that involves impaired or aberrant development of intellectual, motor, or social functions. "Although definitive studies are needed, pilot data suggest that IGF-1 or its analogues are promising for the treatment of the neurodevelopmental disorders associated with ASD." (PMID 28954393, 2017). "Interestingly, many of these genes have been associated with ASD and other neurodevelopmental disorders indicating that caution may be warranted when using IGF-1 on neurotypical controls." (PMID 32591005, 2020). "Because of IGF-1’s function in brain development and its ability to cross the blood-brain barrier, it has emerged as a viable therapeutic method for neurodevelopmental disorders." (PMID 39188438, 2024). "Recombinant IGF-1 and some related compounds have emerged as potential therapeutics for the treatment of neurodevelopmental disorders." (PMID 33414502, 2021). "Post-natally, IGF1 promotes neuronal maturation, and has been shown to partially correct the phenotype of certain neurodevelopmental disorders." (PMID 28203146, 2017). "Previous studies and trials examining IGF-1 as a potential treatment in several childhood-onset neurodevelopmental disorders." (PMID 27746717, 2016). "A second potential action of IGF-1 in these neurodevelopmental disorders includes activation of molecular pathways involved in growth and connectivity (PI3K and MAPK)." (PMID 27746717, 2016). "Ongoing trials examining IGF-1 as a potential treatment in several childhood-onset neurodevelopmental disorders." (PMID 27746717, 2016). "The SYT10/IGF-1 signaling pathway may play a potential key role in Pb-induced neurodevelopmental disorders." (PMID 40559938, 2025). "As IGF-1 plays a role in neurodevelopmental disorders, a growing number of studies have investigated whether there are alterations in IGF-1 levels in children with ASD." (PMID 39188438, 2024). "Thus, our dataset holds promising potential to be used as a future resource by other laboratories worldwide for investigating the relationship between IGF-1 and neurodevelopmental disorders." (PMID 38427732, 2024). "Moreover, IGF-1 has emerged as a potential target for therapeutic approaches in several neurodevelopmental disorders, including ASD." (PMID 34207213, 2021). "Therefore, IGF-1 is currently considered as an ideal drug to treat a large class of neurodevelopmental disorders, including RTT and ASD." (PMID 32063830, 2020). "There are three potential mechanisms by which IGF-1 may exert its effects in these neurodevelopmental disorders." (PMID 27746717, 2016). "Interestingly, many of the genes that were impacted by IGF-1 treatment in controls have been associated with ASD and other neurodevelopmental disorders which may indicate that caution should be used when studying the effects of IGF-1 on neurotypical controls." (PMID 32591005, 2020). "Preliminary evidence is beginning to emerge from well validated murine models and early clinical studies, that treatment with recombinant human IGF-1 (rhIGF-1/mecasermin) and derived compounds may be of benefit in several childhood onset neurodevelopmental disorders." (PMID 27746717, 2016). "Recombinant human IGF-1 has substantial human safety data and is approved for use in children, making IGF-1 an attractive compound for evaluation in neurodevelopmental disorders." (PMID 23621888, 2013). "Changes in insulin-like growth factor-1 levels in maternal plasma from GDM pregnancy might affect the neurodevelopment in offspring, which might become a potential biomarker of neurodevelopmental disorders in GDM offspring." (PMID 41590515, 2026). "In conclusion, we found, for the first time, that IGF-1 can relieve the symptoms of RTT by down-regulating the phosphorylation level of FXYD1, which provides a new therapeutic mechanism for a large class of neurodevelopmental disorders." (PMID 32063830, 2020).
neurodevelopmental disorder (continued). "Here, we review the role of IGF-1 in the molecular etiologies of these conditions in addition to the accumulating evidence from early clinical studies highlighting the possibility of IGF-1 and related compounds as potential treatments for these childhood-onset neurodevelopmental disorders." (PMID 27746717, 2016).
adenocarcinoma (20 papers, 2004 to 2025). A common cancer characterized by the presence of malignant glandular cells. "IGF-1 factor is found to be more highly expressed in adenocarcinomas compared to adenomas and normal colon samples from patients, while IGFBP3 is lower in patients than in healthy individuals." (PMID 31480481, 2019). "Therefore, the level of nuclear FOXO3 is decreased, which prevents FOXO3 from playing an anticancer role and mediates the promotion of adenocarcinoma growth by IGF-1." (PMID 36831629, 2023). "However, it is still unknown or unclear the effect of different DM subclasses on squamous and adenocarcinoma cells at cellular mechanism of IGF-1 levels and overexpression of IGF-1R axis." (PMID 30705329, 2019). "In a transgenic adenocarcinoma of mouse prostate (TRAMP) model, prostate-specific IGF-1 mRNA expression was increased during PCa progression and in the accompanying metastatic lesions." (PMID 36831629, 2023). "Conversely, IGF2BP1 and IGFBP2 expressions significantly correlated with IGF-1 and IGF-2 expressions and adenocarcinoma incidence (p < 0.05)." (PMID 31480481, 2019). "The IGF-1R and its ligands, mainly IGF-1 and IGF-2, have been suggested to play pivotal roles in proliferation, survival and migration of adenocarcinoma cells of the colon/rectum." (PMID 22159423, 2012). "However, a negative correlation between IGF-1 and IGF-1R expressions and caecal/colonic-adherent and fecal viable bacteria was observed (p < 0.05); thus, the significant protection against adenocarcinoma development observed in BF-treated groups is confirmed." (PMID 31480481, 2019).
inflammation (19 papers, 2010 to 2025). Aberrant reaction of the microcirculation characterized by movement of fluid and leukocytes from the blood into extravascular tissues. "As the intestinal microbiota has been demonstrated to play an essential role in the synthesis of IGF-1, it is possible that a dysbiosis condition can cause an uncontrolled production of the growth factor leading to fertility complications and chronic endometrial inflammation." (PMID 35566605, 2022). "In line with previous observations in the related model of pulmonary inflammation, protein synthesis signaling through the IGF-1/Akt/mTOR pathway is reactivated 48 h following LPS in the muscle of WT animals, which signified initiation of muscle mass recovery in that study." (PMID 36807882, 2023). "The IGF1/IGFBP3 ratio is the major predictor of liver inflammation in children with NAFLD." (PMID 37948568, 2023). "Therefore, we next investigated the potential effect of IGF-1 on LPS-induced airway inflammation in vivo." (PMID 32793225, 2020). "Mesenchymal stem cell- (MSC-) derived conditioned medium ameliorates lipopolysaccharide- (LPS-) induced lung injury, by attenuating lung inflammation and promoting a wound healing/anti-inflammatory M2 macrophage phenotype, possibly via paracrine mechanisms involving IGF-1." (PMID 30018981, 2018). "Cows with persistent postpartum uterine inflammation had higher serum concentrations of TNF-α, IL-6, leptin, but lower insulin and IGF-1 compared to normal and spontaneously recovered cows and there was a temporal association observed during the study period." (PMID 24209779, 2013). "Our previous work has also shown that in models of intestinal inflammation, GLP-2 reduces the mucosal content of inflammatory cytokines and TGF-β but increases the macrophage production of IGF-1." (PMID 20953406, 2010). "Chronic inflammation can interfere with the function of GH-IGF-1 axis by inducing relative GH insufficiency, GH/IGF-1 resistance, downregulation of GH/IGF-1 receptors, dysregulation of IGFBPs and thus of IGF-1 bioavailability, impairment of local GH and IGF-1 signaling pathways and gene regulation." (PMID 33712046, 2021). "ATII cell-specific IGF-1 transgenic mice have normal lung pathology, cellularity of BALF, and total lung collagen content, as well as the extent of pulmonary inflammation or fibrosis compared with nontransgenic littermate controls." (PMID 30018981, 2018).
colon polyps (15 papers, 2014 to 2025). "In an Italian cohort, colon polyps were found to be positively associated with GH, IGF-1, fasting glucose, and insulin levels." (PMID 40167828, 2025). "Patients with polyps located in the proximal colon presented significantly higher IGF-1 serum concentrations than did those with distal colon polyps." (PMID 39200386, 2024). "IGF1 is a kind of multifunctional regulatory factor that can facilitate proliferation and inhibit apoptosis in intestinal diseases." (PMID 36274835, 2022). "Elevated IGF-1 levels have been found to promote increased cellular proliferation and anti-apoptotic activity in the colorectal epithelium, which are responsible for the development of colon polyps and malignancies." (PMID 40167828, 2025). "We propose that IGF‐1 signaling might be an attractive target in the context of intestinal diseases with prominent inflammatory cell recruitment." (PMID 29907597, 2018). "It seems that a better understanding of the mechanism of IGF-1, GLP-1 and TL1A on the gut microbiota and inflammation may provide new advances in future therapeutic strategies for patients with IBD, but also other intestinal diseases." (PMID 39594627, 2024).
psychiatric disorder (15 papers, 2014 to 2026). A disorder characterized by behavioral and/or psychological abnormalities, often accompanied by physical symptoms. "In TwinsUK, one CpG of IGF1 was associated with birth weight discordance while there was a 13% average difference in methylation of COMT (implicated in psychiatric disorders) between MZ twins at 5 years." (PMID 30096154, 2018). "Thus, we suggest that drugs which target the IGF-1 pathway should be evaluated for the treatment of psychiatric disorders associated with impaired glutamate function." (PMID 25061506, 2014). "Substantial evidence indicates neurotrophic/growth factors such as BDNF and IGF-1 are involved in the pathogenesis of common psychiatric disorders." (PMID 25734326, 2015). "As ghrelin has initially been described as a powerful GH secretagogue and a number of studies have focused on its role as a regulator of the GH/IGF-1 axis, the link between ghrelin, GH axis, and psychiatric disorders needs to be questioned." (PMID 25386163, 2014). "Plasma concentrations of BDNF, IGF-1 and IGFBP-3 in abstinent cocaine users grouped by diagnosis of common psychiatric disorders in substance users." (PMID 25734326, 2015).
brain diseases (14 papers, 2012 to 2025). "Recently, it has been suggested that inhibition of IGF1 signaling induces developmental defects in mice that resemble human preterm brain disorders, which can be reversed with a GABAergic modulator." (PMID 40457513, 2025). "A new large-sample study shows a strong link between high and low IGF-1 concentrations and brain disease, highlighting the potential of IGF-1 as a biomarker for stratifying brain health risks." (PMID 38919642, 2024). "Furthermore, our data suggest patient stratification (possibly based on IGF-1 levels together with absence of brain lesions) in future clinical trials with recombinant human IGF-1 (and analogous drugs) for the treatment of preterm-related brain disorders." (PMID 38427732, 2024). "Importantly, IGF-1 can pass through the blood-brain barrier, making it possible to treat brain disorders with peripheral administration of IGF-1." (PMID 32063830, 2020). "The IGF-1 signaling pathway is involved in numerous brain diseases." (PMID 31787098, 2019). "Here, we showed that transient IGF-1 signaling inhibition during the mouse counterpart of the human third trimester of pregnancy resulted in brain microstructural, functional, and behavioral alterations in mice resembling brain disorders typical of children born preterm nowadays." (PMID 38427732, 2024). "Given the well-established neuroprotective functions of circulating IGF-1, compromised BBB transport may represent a fundamental pathophysiological mechanism common to various brain disorders, as we previously proposed." (PMID 41155299, 2025). "We discuss how BDNF, NGF, IGF-1, and LIF could potentially be used for the treatment of brain diseases." (PMID 39598254, 2024). "Our data indicate that IGF-1 signaling during the time window of prematurity is an essential neurotrophic factor and suggest GABAAR PAMs as a potential strategy to address preterm brain disorders later in life." (PMID 38427732, 2024). "On the basis of the anti-inflammatory effects of IGF-1, it has been suggested that development of resistance to IGF-1 may contribute to neuroinflammation and progression of major brain diseases." (PMID 29163145, 2017). "CPEC proliferation in response to scratch injury, and its further enhancement by IGF-1/EGF, may have significance in human brain disorders." (PMID 25815836, 2015).
immune dysfunction (14 papers, 2013 to 2026). "Postulated systemic impacts include vascular ischemia, immune dysfunction, oxidative stress, and dysregulated angiogenesis, along with derangements of the insulin-like growth factor-1 (IGF-1) axis." (PMID 36331687, 2023). "Relative Energy Deficiency in Sport (RED-S) has been reported in male and female elite athletes and impairs endocrine response (i.e., cortisol, insulin, IGF-1, adipokines, incretins), contributing to metabolic and immune dysfunction." (PMID 36615810, 2022). "Frequent infections and immune dysfunction in early childhood can lead to transient growth delays, primarily through the action of pro-inflammatory cytokines which suppress the growth hormone (GH)–insulin-like growth factor-1 (IGF-1) axis." (PMID 40429990, 2025). "Cortisol and other hormones such as insulin, IGF-1, modulated by RED-S also could contribute to immune dysfunction." (PMID 31686980, 2019). "However, IGF-1 signaling is impaired in diabetic patients, and T cells from diabetic wounds often lack the ability to produce IGF-1, contributing to delayed wound healing and immune dysfunction 21,56,61." (PMID 41328337, 2026).
myopathy (13 papers, 2010 to 2023). A disease of the muscle in which the muscle fibers do not function properly. "Myopathy caused by chronic ethanol exposure seems to be related to reduced mRNA expression of insulin-like growth factor 1 (IGF-1) polypeptide, insulin, IGF-1, and IGF-2 receptors, insulin receptor substrate (IRS) 1, and IRS-2." (PMID 30477112, 2018). "Skeletal muscle abnormalities including widespread myopathy phenotype with atrophy, decreased insulin-like growth factor-1 (IGF-1) signaling, increased oxidative stress, and impaired functionality have been observed in experimental and clinical studies." (PMID 36829850, 2023). "The decrease in insulin/IGF1 signaling leads to myopathy through downregulation of the Kit ligand and the ERK signaling pathways." (PMID 37759758, 2023). "Of interest, the restoration of IGF-1 signalling can rescue GC induced myopathy in mice, demonstrating a crucial role for this growth factor in the process of GC-induced myopathy." (PMID 31744114, 2019). "In animal models, there are studies showing damage to the diaphragmatic structure after administration of systemic steroids, with proteolysis and downregulation of IGF-1 being the plausible mechanisms responsible for steroid-induced myopathy." (PMID 29703214, 2018). "Although growth hormone (GH) and insulin-like growth factor-1 (IGF-1) levels are associated, albeit not indisputable, with the presence and severity of ACRO myopathies the precise effects attributed to increased GH or IGF-1 levels are still unclear." (PMID 33401779, 2021). "Although the duration of the disease and serum GH/IGF-1 levels were shown to be independent predictors of overall mortality and co-morbidities of ACRO, their specific role in the pathogenesis of myopathy remains to be elucidated." (PMID 33401779, 2021).
bacterial infection (9 papers, 2014 to 2025). "Significantly, the DAF-16/FOXO transcription factor, a key component of the insulin/IGF-1 signaling pathway, has been identified as a crucial immune regulator in the defense against bacterial infections." (PMID 39728497, 2024). "Smaller pilot studies, which short follow-up periods, have revealed no increased short-term risk of bacterial infections related to IGF-1 supplementation." (PMID 37648745, 2024). "daf-2 insulin/IGF-1 signaling (IIS) mutants are long-lived and exhibit increased resistance to bacterial infection." (PMID 40909712, 2025). "Given that the insulin/IGF-1 signaling pathway and the p38 MAPK pathway in C. elegans are required for the defense response against several bacterial infections in intestine, we examined the role of these pathways against P. luminescens." (PMID 25279274, 2014). "In bacterial infection of rainbow trout (Oncorhynchus mykiss), a strong correlation between IGFBP-1A1 and IGFBP-6A2 in the GH/IGF axis and proinflammatory cytokine genes was found, which suggested a relationship between IGF-1 and the immune response against bacteria." (PMID 36016944, 2022). "Having an immune-regulatory effect in addition to their anabolic effects, growth hormone (GH) and insulin-like growth factor 1 (IGF-1), may act to protect the host from lethal bacterial infection as well." (PMID 33240216, 2020). "Likewise, insulin/insulin-like growth factor (IGF) signaling, through the insulin/IGF-1 transmembrane receptor homolog DAF-2, integrates nutritional cues and fat utilization to enable survival during bacterial infection." (PMID 37906605, 2023).
hematologic malignancies (8 papers, 2014 to 2025). "Insulin-like growth factor-1 (IGF-1) is a growth factor that has a role in the progression of solid and hematologic malignancies." (PMID 33105727, 2020).
bone disorder (7 papers, 2018 to 2025). "Meanwhile, IGF-1 plays a vital role in bone growth and homeostasis, and its decreased levels are associated with bone disorders." (PMID 36010307, 2022). "Insulin-like growth factor 1 (IGF-1) plays an important role in bone growth and maintenance, and its decreased levels are associated with bone disorders." (PMID 36010307, 2022). "Accordingly, decreased IGF-1 levels could lead to low bone mass, bone disorders and high fracture risk, as suggested in this study." (PMID 36010307, 2022). "Furthermore, the association of serum IGF-1 levels with bone disorders, the FRAX and high fracture risk was investigated." (PMID 36010307, 2022). "Serum IGF-1 levels were associated with bone disorders and the FRAX-derived fracture risk, and may be a useful indicator for initiating therapeutic intervention to prevent the incidence of fracture in patients with PBC." (PMID 36010307, 2022). "The cutoff values of IGF-1 for predicting these bone disorders were 61.5 ng/mL (area under the curve: 0.74; sensitivity/specificity: 0.545/0.894), 69.5 ng/mL (0.70; 0.633/0.784) and 61.5 ng/mL (0.74; 0.512/0.929), respectively." (PMID 36010307, 2022). "The prevalence of these bone disorders significantly increased stepwise with decreasing serum IGF-1 levels (p < 0.001 and p = 0.001, respectively)." (PMID 36010307, 2022).